VIM (vimentin)
Diseases named in the same sentence as VIM in open-access papers (continued):
Sharing a sentence is not in itself a finding about the gene and the disease.
breast tumor (64 papers, 2006 to 2025). "The co-expression of cytokeratins and vimentin has been described in breast tumors associated to malignancy." (PMID 25807360, 2015). "In contrast, re-expression of KLK6 at physiological concentrations dramatically inhibits the growth of primary breast tumors and causes marked reduction of vimentin." (PMID 21072173, 2010). "Moreover, knockout of TWIST1 has been found to significantly reduce the number of Vimentin-positive breast tumor cells, which indicates that Twist1 expression is positively associated with Vimentin expression." (PMID 35052775, 2022). "According to a previous study, ZEB1 and ZEB2 repress E-cadherin expression, whereas ZEB2 directly interacts with the vimentin promoter in human epithelial breast tumor cells." (PMID 41002590, 2025). "In vivo animal experiments showed that knockdown of eIF4E expression significantly inhibited breast tumor growth volume, while immunohistochemistry showed that knockdown of eIF4E decreased the expression of the mesenchymal marker vimentin." (PMID 37217473, 2023). "We also reported that the intermediate filament vimentin is able to prevent a miR-dependent negative regulation of TF in breast tumor cell lines." (PMID 35805061, 2022). "Studies of EMT markers in “basal-like” breast tumours reported that EMT markers (vimentin), as well as cadherin switching (reduced expression of E-cadherin), were significantly more frequent." (PMID 35884609, 2022). "On these premises, we aimed to investigate the relationships between TG2 and motility in breast tumor cells in greater detail, focusing on vimentin, which represents an important element of the filamentous cytoskeleton and a pivotal marker of EMT." (PMID 34831282, 2021). "This study also examined the expression of CSCs markers (CD44 and CD24) and EMT markers (E-cadherin, β-catenin, vimentin, and N-cadherin) in the isolated breast tumor cells and in tumor tissues by qRT-PCR." (PMID 33282946, 2020). "Consistent with our published studies, p66ShcA increases Vimentin expression in ErbB2+ luminal breast tumors (NIC) whereas E-Cadherin levels are largely unaffected compared to control tumors." (PMID 31941526, 2020). "Of particular interest are the immunohistochemical analyses where the co-expression of epithelial (E-cadherin or keratins) and mesenchymal (N-cadherin or vimentin) markers was initially characterized in different breast tumour series." (PMID 31091749, 2019). "We determined if the effects of baicalein on the expression of FN, calpain-2, E-cadherin, and vimentin in breast tumor tissue reflected the in vitro results." (PMID 31000696, 2019). "Consistent with the in vitro results, baicalein reduced FN and vimentin expression but increased E-cadherin expression in breast tumor tissue of MMTV-PyMT mice compared with control mice at the same stage." (PMID 31000696, 2019). "Co-staining for CEACAM5 and vimentin revealed higher levels of CEACAM5 in the lung metastasis relative to matched breast tumor, and the reverse staining pattern was observed for vimentin." (PMID 29736411, 2018). "By staining breast tissue sections with H&E, cytokeratin and vimentin, we identified distinct structural and compositional changes to the breast tumour microenvironment." (PMID 30348208, 2018). "The human breast tumor biomarker miR-30c can inhibit tumor invasion by targeting the cytoskeletal network genes encoding TWF1 and vimentin." (PMID 28159933, 2017). "Immunofluorescence staining further showed increased staining of E-cadherin and less staining of vimentin in the cytoplasm and the membranes of breast tumor cells expressing DKK2." (PMID 28467796, 2017). "In vitro data also revealed that 4T1 mouse breast tumor cells showed higher rate of migration and invasion along with decreased E–cadherin and increased N-cadherin and vimentin levels after fractionated radiation." (PMID 27462787, 2016).
breast tumor (continued). "ER-negative breast tumors express higher levels of vimentin than ER-positive tumors and in vivo expression of vimentin correlates strongly with more malignant breast tumor phenotypes." (PMID 25749031, 2015). "We assessed the correlation between the level of NEDD9 and that of the mesenchymal markers, such as Vimentin and Fibronectin in 32 aggressive breast tumors." (PMID 21829474, 2011). "It is interesting to note that in breast tumor cells, vimentin filament assembly plays a direct role in the stability of a type of cellular protrusions, called tubulin microtentacles, that are involved in tumor invasiveness." (PMID 20169076, 2010). "Furthermore, lower expression of vimentin that was correlated with overexpressed miR-30a-5p inhibited breast tumor progression in another study." (PMID 31217934, 2019). "Since loss of E-cadherin is a marker of EMT, it might be worthwhile to examine other EMT markers such as MMPs, which lead to E-cadherin degradation, or vimentin in multicentric/multifocal versus unifocal breast tumors." (PMID 23890049, 2013). "This is also in concordance with a previous immunohistochemical study of 491 breast tumors where high expression of mesenchymal markers (i.e., vimentin, N-cadherin) and low expression of CDH1 were found almost exclusively in the triple-negative subgroup of tumors." (PMID 20813035, 2010). "However, more alarming is the fact that nicotine could contribute to breast tumor metastasis by increasing the expression of a GTPase, cdc42, as well as vimentin, which promotes epithelial to mesenchymal transition (EMT), a key step in metastasis." (PMID 33414685, 2020). "We found that Brazilin significantly affects the upregulation of EMT markers vimentin and Twist and the invasion of highly invasive MDA-MB-231 breast tumor cells of the TNBC subtype." (PMID 38737746, 2024). "In breast tumors the expression of Cx46 (atypical connexin for breast tissue) increased the expression of EMT markers, namely, N-cadherin, vimentin, Snail and Zeb1, and stemness markers." (PMID 36829482, 2023). "For that purpose, we transfected siRNA sequences against vimentin (Vim Si1 and Vim Si2) in well-known EMT+ MDA-MB-231 human breast tumor cells and in human cell systems previously reported to be inducible for EMT by EGF (MDA-MB-468, PMC42-LA) or TGF-β1 (Α549)." (PMID 32152404, 2020). "Tissues from patients with metastatic breast cancer confirmed elevated levels of CEACAM5 in lung metastases relative to breast tumors, and an inverse correlation between CEACAM5 and the mesenchymal marker vimentin was demonstrated." (PMID 29736411, 2018). "CDH1 and ELF3 were expressed at a significantly higher level in cells with an epithelial morphology, whereas FN1, FOSL1, VIM, ZFHX1B, SNAI2, SERPINE1 and TFGB1 showed a higher expression in fibroblastic breast tumour cells." (PMID 16495925, 2006). "This revealed that both EPI (e.g. LLGL2, CLDN4, KRT7, ST14) and MES (e.g. SNAI1, VIM, AP1M1) genes positively correlated with PIEZO1 expression across all quintiles, whilst markers of luminal breast tumors (ESR1, FOXA1, PGR) negatively correlated in all instances." (PMID 38632473, 2024). "The majority of the breast tumour cells in this lung metastasis expressed detectable E‐cadherin and RFP and lacked vimentin, although the surrounding lung cells in the host organ were vimentin‐positive." (PMID 35348275, 2022). "Notably, the homogeneous distribution of the epithelial marker cytokeratin and the mesenchymal marker vimentin in the alginate–fibrin, PCL, and fibrin groups, confirms the formation of an engineered breast tumor tissue via the AV model." (PMID 35877331, 2022). "We, however, did not see an inverse correlation between FRK and Fibronectin/Vimentin in the breast tumor samples." (PMID 29348886, 2017).
breast tumor (continued). "Consistent with the correlation of miR-100 with EMT markers, the luminal A subtype of primary breast tumors (which are known to be E-cadherin-positive and vimentin-negative) exhibited the most significant downregulation of miR-100." (PMID 24586203, 2014). "Eighty-six breast tumors and one normal breast sample from the UNC337 database, including 20 claudin-low tumors, were evaluated using dual immunofluorescence (IF) staining with epithelial (keratin 5/19) and mesenchymal (vimentin) markers." (PMID 20813035, 2010). "For example, aberrant STAT3 signaling promotes breast tumor progression through deregulation of the expression of downstream target genes, which control proliferation (Bcl-2, Bcl-xL, survivin, cyclin D1, c-Myc, and Mcl-1), angiogenesis (Hif1α and VEGF), and EMT (vimentin, Twist, MMP-9, and MMP-7)." (PMID 36446524, 2023). "Furthermore, N-Cadherin expression was down-regulated in the breast tumor tissues in Pp2cm knockout mice compared with that in control mice, but the expression of E-Cadherin and Vimentin was not changed." (PMID 35785192, 2022). "However, cotreatment with both MEC plus SB 203580 was more effective in further reducing tumor volumes as well as attenuating protein expression of both SOX2 and vimentin, suggesting a casual role of both nicotine and p38 MAPK in NIC plus HFD-induced breast tumor progression." (PMID 33414685, 2020). "In breast tumor-derived cells, we failed to observe any significant correlation between Vav1 and the expression levels of the epithelial marker E-cadherin as well as of the mesenchymal protein Vimentin." (PMID 24962430, 2014). "The METABRIC database (1904 human breast tumors) consistently revealed a positive association of NME4 with epithelial markers CDH1 and KRT18 and a negative association with mesenchymal markers CDH2 and VIM as well as many EMT drivers like ZEB1, ZEB2, SNAI2, TWIST1, and TWIST2." (PMID 34674701, 2021). "Interestingly, our data showed that CAFs exposed to the treatment with the PPARγ agonist BRL acquired a phenotype characterized by a decreased expression of α-SMA/vimentin and CXCR4 together with a reduced migratory capability, all features that may negatively impact breast tumor progression." (PMID 27556298, 2016).
non-small cell lung carcinoma (64 papers, 2008 to 2025). A group of at least three distinct histological types of lung cancer, including non-small cell squamous cell carcinoma, adenocarcinoma, and large cell carcinoma. "Very interestingly, EndMT is also described for circulating tumor endothelial cells: double-positive circulating tumor endothelial cells (CD31+-vimentin+) were found in blood samples from patients with non- small-cell-lung cancer (NSCLC)." (PMID 40650130, 2025). "Subsequently, nuclear β-catenin binds to transcription initiation sites, fostering the high expression of downstream proteins such as Vimentin and N-cadherin, which in turn promotes the proliferation, migration, and invasion of non-small cell lung cancer." (PMID 40352786, 2025). "For example, CRISPR/Cas9 gene editing was used to generate a vimentin red fluorescent protein (RFP) fusion reporter in a non-small cell lung cancer (NSCLC) cell line for real-time tracking of EMT status, resulting in the discovery of two EMT inhibitors." (PMID 39926198, 2025). "Vasculogenic mimicry and expression of slug and vimentin correlate with metastasis and prognosis in non-small cell lung cancer." (PMID 40786517, 2025). "The expression levels of markers, such as E-cadherin, which maintains adhesive junctions, and vimentin, which is involved in cytoskeletal remodeling, are significantly related to the prognosis of non-small cell lung cancer (NSCLC)." (PMID 40304000, 2025). "A meta-analysis of 4118 non-small cell lung cancer cases revealed a significant odds ratio of 1.631 (p-value = 0.029) for disease recurrence to increased vimentin expression." (PMID 35207438, 2022). "They showed that high expression of VIMENTIN and invasive ability was reduced in non-small cell lung cancer cell lines by knockdown of VIMENTIN." (PMID 35178358, 2021). "High expression of VIM was found in esophageal squamous cell carcinoma and non-small cell lung cancer tumors with much more advanced tumor status and a higher incidence of lymph node metastasis." (PMID 33330445, 2020). "Jefri and his colleague in their study proposed that YKL-40, one member of chitinase family, regulated EMT and migration/invasion enhancement by detecting the EMT markers such as Twist, N-cadherin, Vimentin, and E-cadherin in non-small cell lung cancer." (PMID 31238895, 2019). "Other PI3K inhibitors, LY294002 and BEZ-235 have also inhibited EMT process by increasing expression of Ecadherin and decreasing those of Vimentin and Fibronectin in lens epithelial cells and non-small cell lung cancer cells." (PMID 27793006, 2016). "Expression of the mesenchymal marker vimentin in epithelial cells of pancreatic and non-small cell lung carcinomas is correlated with poor prognosis." (PMID 27253518, 2016). "Such cells were detected five years ago in patients with metastatic non-small cell lung cancer (NSCLC) by a fluorescent co-staining of vimentin and cytokeratins." (PMID 27529216, 2016). "Herein we validate a small molecule inhibitor of GLS and show that non-small cell lung cancer cells marked by low E-cadherin and high vimentin expression, hallmarks of a mesenchymal phenotype, are particularly sensitive to inhibition of the enzyme." (PMID 25502225, 2014). "Factors such as E-cadherin, catenins, vimentin, and snail have all been correlated with clinical and pathological features in non-small-cell lung cancer." (PMID 24274066, 2013). "Furthermore, studies have demonstrated that demonstrated that METTL3 overexpression increased vimentin expression in human non-small cell lung cancer cells." (PMID 41345738, 2025).
non-small cell lung carcinoma (continued). "Moreover, EV-mediated transfer of miR-122-5 upregulated N-cadherin and Vimentin and downregulated E-cadherin in hepatocytes in non-small cell lung cancer (NSCLC), thereby regulating PMN-promoting cell–ECM adhesions." (PMID 37350937, 2023). "The O-methylated flavonol rhamnetin and the natural flavonoid cirsiliol overcame radioresistance via the downregulation of Notch1, Ciap1, Ciap2, survivin, vimentin, and fibronectin and the up-regulation of E-cadherin in radio-exposed non-small cell lung cancer cells." (PMID 37240422, 2023). "Moreover, TGFβ1 was shown to increase the expression of EMT markers N-cadherin and vimentin in the non-small-cell lung cancer cell line." (PMID 36551653, 2022). "Furthermore, BANCR expression promoted non-small cell lung cancer cell migration and invasion through regulating E-cadherin, N-cadherin and Vimentin expression, all of which play crucial roles in epithelial-mesenchymal transition (EMT)." (PMID 27514530, 2016). "Furthermore, EV-mediated transfer of miR-122-5p has been shown to regulate PMN formation by modulating cell–ECM adhesion; it upregulates N-cadherin and vimentin while downregulating E-cadherin in hepatocytes, as seen in non-small cell lung cancer (NSCLC) models." (PMID 40149289, 2025). "Furthermore, rhamnetin and cirsiliol have been demonstrated to display anticancer effects and the ability to sensitize radioresistant cells through the inhibition of EMT markers, including fibronectin, vimentin, and E-cadherin, in non-small cell lung cancer cells." (PMID 39770941, 2024). "In non-small cell lung cancer (NSCLC), CCL2 reduces E-cadherin levels and upregulates vimentin, MMP-2 and MMP-9 protein levels through PI3K/Akt/mTOR to activate EMT." (PMID 41341593, 2025). "In non-small cell lung cancer (NSCLC), cells treated with the epidermal growth factor receptor (EGFR) inhibitor gefitinib exhibited reduced E-cadherin levels and increased vimentin expression in resistant cells." (PMID 40738896, 2025). "For example, in a non-small cell lung carcinoma cell line, binding of NANOS3 protein to vimentin mRNA regulated the length of the poly(A) tail and prevented microRNA-mediated repression of vimentin, causing an increase in the invasive potential of these cells." (PMID 35207438, 2022). "Increased vimentin provides stability to FAK through VAV2-mediated Rac1 activation that increases the motility and invasiveness in non-small cell lung cancer." (PMID 35573702, 2022). "Vimentin and CD133 tumor expression were evaluated in samples from 36 patients with EGFRm non-small cell lung cancer through immunohistochemistry." (PMID 34771484, 2021). "Our previous study revealed that EGCG increased the stiffness of H1299 and Lu99 human non-small cell lung cancer (NSCLC) cells, inhibited the high expression of EMT-related proteins, such as vimentin and SLUG, and reduced cell motility." (PMID 32051483, 2020). "SNHG12 overexpression promoted cell invasion, migration, and EMT in non-small cell lung cancer via engaging into Slug/ZEB signaling pathway to regulate expression of E-cadherin, matrix metalloproteinase 9 (MMP-9) and vimentin." (PMID 33124951, 2020). "First, we examined TGFβ responsiveness in three non-small-cell lung carcinoma (NSCLC) cell lines (HCC827, A549, H3255) towards bulk expression of widely accepted EMT markers (E-Cadherin, Vimentin, CD442,4,17)." (PMID 31811131, 2019). "Notably, exosomes from HPV-16 E7-expressing non-small cell lung cancer (NSCLC) cells dramatically promoted EMT, evidenced by the upregulation of mesenchymal markers (Vimentin, N-cadherin, Snail1, Slug, Twist1) and suppression of E-cadherin." (PMID 41154440, 2025). "Clinical feasibility was investigated by analyzing whole blood specimens from non-small cell lung cancer (NSCLC) patients and cholangiocarcinoma patient, using the epithelial marker EPCAM and the epithelial–mesenchymal transition (EMT) biomarkers vimentin and MET." (PMID 32486306, 2020).
non-small cell lung carcinoma (continued). "FN1, together with E-cad and VIM, serves as a marker for EMT in non-small cell lung cancer." (PMID 32697311, 2020). "Moreover, GLUT3 expression correlates with both EMT markers (i.e., vimentin, Snail, Slug, ZEB1, ZEB2, Twist1) and glucose uptake in non-small cell lung cancer (NSCLC) cells." (PMID 28352611, 2017). "Vimentin is a member of the intermediate filament proteins and a canonical marker of the epithelial-mesenchymal transition (EMT), which is pivotal in tumorigenesis, metastasis and invasion in non-small cell lung cancer (NSCLC)." (PMID 27657690, 2016). "In cervical, HNSCC and non-small cell lung cancer (NSCLC) cells, IL-6 induces a similar pro-mesenchymal morphology, cell scattering, motility and invasion, and decreases E-cadherin and increases N-cadherin and vimentin levels in vitro and in xenografts in nude mice." (PMID 34361105, 2021). "Non-small cell lung cancer (NSCLC) cell lines sensitive to gefitinib express EMT markers such as E-cadherin, claudin-4 and claudin-7, but resistant cell lines have lost expression of these genes, while the mesenchymal marker vimentin was highly expressed in the resistant cell lines." (PMID 27757846, 2017).